GCG (glucagon)
Diseases named in the same sentence as GCG in open-access papers (continued):
Sharing a sentence is not in itself a finding about the gene and the disease.
type 2 diabetes (continued). "The disrupted coordination of glucagon and insulin secretion observed in type 2 diabetes is characterized by impaired and delayed insulin secretion as well as basal hyperglucagonemia and non-suppressed glucagon secretion in response to glucose." (PMID 30849121, 2019). "In summary, this paper aimed to develop the hypothesis of the existence of type 2 diabetes with HA1A subgroup, characterized by a common diabetogenic mechanism via glucagon synergism, and more importantly, a specific pattern of complications." (PMID 30820389, 2018). "Furthermore, GCGR knockdown abolished the glucagon-mediated deactivation of AMPK and activation of MAPK, resulting in induction of an inhibitory effect of tumor growth in type 2 diabetes model mice." (PMID 29535833, 2018). "In type 2 diabetes model mice, there were distinct differences in tumor growth between control and GCGR knockdown clones, even though the concentrations of plasma blood glucagon in mice are much lower than in cell culture media used for in vitro studies." (PMID 29535833, 2018). "On the basis of the lack of severe hypoglycemia, the lesson learned was that glucagon antagonism appears relatively safe and therefore a potential therapy for type 2 diabetes." (PMID 28323959, 2017). "We recently have reported the 24-hour glucose, insulin and glucagon responses to a 72-hour fast compared to a 72-hour macronutrient-sufficient, no-carbohydrate diet in men with type 2 diabetes." (PMID 27453716, 2016). "It is important to note that glucagon levels are abnormally high in the specific context of hyperglycemia and hyperinsulinemia, whereas in untreated type 2 diabetes the level is sometimes not elevated in absolute terms." (PMID 25961284, 2015). "Inhibiting the interaction between glucagon and its receptor has been reported to control hepatic glucose overproduction and thus GCGR has evolved as an attractive therapeutic target for the treatment of type II diabetes mellitus." (PMID 25521597, 2014). "The authors also suggest that the elevated levels of glucagon and increasing insulin resistance result in nonsuppressible hepatic glucose production in type 2 diabetes patients." (PMID 26317099, 2013). "Stevioside was able to lower blood glucose in type 2 diabetic subjects and in a non-obese animal model of type 2 diabetes i.e. the Goto Kakizaki rat by both increasing insulin release and suppressing glucagon levels." (PMID 22479612, 2012). "Small intestinal nutrient did not suppress glucagon in critically ill patients with type-2 diabetes during either placebo or GLP-1 infusion." (PMID 21255422, 2011). "Therefore, the relative role of a direct blockade of glucagon signaling in the liver and the indirect effects of GCGR blocker treatment leading to an elevation of plasma GLP-1 on the improvement of hyperglycemia in type 2 diabetes remains to be clarified." (PMID 38265288, 2024). "Treatment for type 2 diabetes should aim to reduce, rather than increase, the effects of glucagon." (PMID 39211720, 2024). "Research has shown that glucagon stimulates gluconeogenesis through the liver lipolysis mediated by inositol triphosphate receptor 1 (INSP3R1), suggesting that INSP3R1 may be a new target for the treatment of type 2 diabetes." (PMID 39635431, 2024). "Insulin, C-peptide and glucagon concentrations in subjects with and without type 2 diabetes." (PMID 37751301, 2023). "However, a lack of understanding of the mechanisms that control glucagon secretion has made it difficult to provide treatments that directly target the dysregulated glucagon secretion in both type 1 and type 2 diabetes." (PMID 35237171, 2022). "We hypothesized that alanine, rather than glutamine, would be a predominant stimulator of glucagon secretion in patients with type 2 diabetes." (PMID 34382579, 2021). "Interestingly, GLP-1 secretion failed to inhibit glucagon secretion after oral glucose in participants with type 2 diabetes (p = 0.0035)." (PMID 32385603, 2020).
type 2 diabetes (continued). "Furthermore, some, but not all, subjects with type 2 diabetes show elevated glucagon concentrations in the fasting state and sometimes fail to suppress postprandial glucagon secretion." (PMID 31284506, 2019). "Research during the coming years may provide answers to whether or not glucagon agonism/antagonism will reach clinical application for treatment of metabolic diseases such as obesity and type 2 diabetes." (PMID 31284506, 2019). "Although hypersecretion of glucagon after ingestion of glucose or mixed meal is well known in type 2 diabetes, this might not be observed in this study because our participants had only mild type 2 diabetes." (PMID 26704625, 2016). "Sitagliptin is an oral medication indicated for type 2 diabetes mellitus (T2DM) and prevents inactivation of GLP-1 by selectively inhibiting DPP-4, thus increasing insulin secretion and decreasing glucagon concentration in a glucose-dependent manner." (PMID 23056044, 2012). "The original finding that GLP-1 infusion increased insulin release and reduced fasting plasma glucose and glucagon in Type 2 diabetic subjects resulted in the development of the first GLP-1 receptor agonists, and the recent licensing of exenatide for the treatment of Type 2 diabetes." (PMID 18959599, 2008). "While its insulinotropic action is reportedly attenuated or abolished with worsening of glycaemic control in type 2 diabetes (T2D), the relationship between GIP and glucagon secretion across different levels of glycaemic control remains unclear." (PMID 41943672, 2026). "On pancreatic islets, GLP-1 RAs stimulate glucose-dependent insulin release and inhibit glucagon secretion, improving postprandial glucose control without provoking hypoglycemia—an important feature for insulin-resistant youth and those with prediabetes or type 2 diabetes." (PMID 41300545, 2025). "However, while the contribution of pancreatic β-cells has been well studied, the contribution of α-cell dysfunction to the pathogenesis of type 2 diabetes remains understudied in part due to the lack of appropriate methodologies to accurately assess glucagon secretion and action." (PMID 37030857, 2023). "Some of the drugs often used in patients with type 2 diabetes (T2D), such as furosemide or acetylsalicylic acid, may influence prostaglandins (PG) synthesis, mainly PGE, which in turn control glucagon release." (PMID 27568179, 2016). "A regulatory mechanism involving a cooperative interaction between insulin and glucagon may have evolved to allow for the induction of FGF21 gene expression during a broad range of stress conditions including starvation and diseases arising from overnutrition (e.g. type 2 diabetes)." (PMID 24733293, 2014). "Hyperglucagonemia, a hallmark of type 2 diabetes (T2DM) present in Zucker diabetic fatty (ZDF) rats, is not the primary mediator of hyperglycemia and high EGP as commonly thought; instead, the liver is resistant to glucagon as well as insulin and glucose." (PMID 38265288, 2024). "Stevia, compared to maize starch has also been shown to decrease glucagon and glucose (but not Glucagon-like Peptide-1 (GLP-1) or Gastric Inhibitory Peptide (GIP)) in patients with type 2 diabetes." (PMID 38553262, 2024). "In people without type 2 diabetes, exendin 9-39 — presumably through GLP1R blockade — decreases insulin secretion in response to glucagon." (PMID 37751301, 2023). "In the vagotomised subjects, a lack of glucagon suppression was reported following OGTT, similar to early steps in the development of type 2 diabetes." (PMID 38059537, 2023). "Type 2 diabetes mellitus (T2DM) is a prevalent non-communicable disease characterized by hyperglycemia resulting from the combination of defects in insulin secretion, resistance to insulin action, and excessive glucagon secretion." (PMID 32754118, 2020).
Hypoglycemia (845 papers, 1998 to 2026). A decreased concentration of glucose in the blood. "Patients are also vulnerable to life-threatening hypoglycemia, driven largely by defective α-cell glucagon secretion, yet the mechanisms underlying this counterregulatory failure remain poorly understood." (PMID 42040939, 2026). "The process boosts glucose-dependent insulin production while reducing glucagon release from the pancreatic α-cells, resulting in decreased blood sugar levels and a minimized risk of hypoglycemia because of increased insulin and decreased glucagon secretion." (PMID 40422559, 2025). "In the differential diagnosis, elevated serum glucagon can also be caused by hypoglycemia, fasting, trauma, sepsis, acute pancreatitis, abdominal surgery, Cushing’s syndrome, and renal and hepatic failure." (PMID 40941664, 2025). "It should minimise the risk of hypoglycaemia, ideally by replicating the counter-regulatory effect of glucagon, and adapt to diurnal variations in insulin sensitivity influenced by factors such as physical activity, sleep, and hormonal changes." (PMID 40718205, 2025). "With regard to the occurrence of acute decompensations in the past year, 7.62% presented at least one DKA, 6.88% hyperglycemia requiring emergency care, and 2.79% hypoglycemia with loss of consciousness and administration of glucagon." (PMID 39860531, 2025). "The observed rise in glucose following glucagon suggested a pre‐receptor or post‐receptor pathology involving insulin or insulin‐like activity as the cause of hypoglycemia." (PMID 40697895, 2025). "This approach addresses the limitations of existing systems by providing self‐regulating glucagon release, reducing the risk of hypoglycemia, and achieving long‐term glycemic control for over 24 h." (PMID 39887601, 2025). "Under physiological conditions, hypoglycemia stimulates the secretion of glucagon, which causes the mobilization of fat to produce fatty acids and glycerol." (PMID 40980340, 2025). "Along with β-cell destruction, another key pathophysiologic feature of T1D is dysregulated glucagon secretion with deficient glucagon response to hypoglycemia and exaggerated glucagon release following a meal." (PMID 40760325, 2025). "The prominent decrease in plasma glucagon concentrations in Pcsk2αcell−/− mice raised the question of increased susceptibility to hypoglycemia." (PMID 40971442, 2025). "Insulin therapy should be used with caution because of the risk of hypoglycemia due to the impaired glucagon function inherent to Type 3c diabetes." (PMID 40143090, 2025). "People with T1DM exhibit an impaired glucagon response to hypoglycemia, which increases the risk of severe hypoglycemia." (PMID 39996055, 2025). "It is conceivable that glucagon is associated with sympathetic tone because hypoglycemia activates the stress response and the hypothalamic–pituitary–adrenal axis." (PMID 39594592, 2024). "We found that the increases in plasma glucagon levels caused by insulin-mediated hypoglycemia or 2-DG-induced glucopenia were significantly reduced in α-GsKO mice, as compared to control littermates." (PMID 38879678, 2024). "Another study in mice identified Agpat5 within a genome-wide significant QTL associated with hypoglycemia-induced glucagon secretion." (PMID 39608054, 2024). "We postulate that the combination of a PBH-like syndrome and reduction in protective mechanisms against hypoglycemia, including deficient glucagon responses to hypoglycemia, likely explain the effectiveness of liraglutide in our patient." (PMID 39450137, 2024). "There is some evidence that PBH and hypoglycaemia during mixed meal testing and during continuous glucose monitoring are associated with alterations in glucagon secretion." (PMID 38451861, 2024). "Lixisenatide stimulates insulin secretion when blood glucose is elevated but not when blood glucose is normal, thereby circumventing the risk of hypoglycemia and glucose-dependently inhibiting glucagon secretion." (PMID 39598478, 2024).
Hypoglycemia (continued). "This dysfunction is characterized by inappropriate glucagon secretion, augmenting the risk of life-threatening hypoglycemia." (PMID 39594662, 2024). "The increased demand for glucose in cancer cells which can cause hypoglycemia, increasing compensatory hormone signals, growth hormones, epinephrine, or glucagon." (PMID 38273418, 2024). "Recently, impaired autocrine glutamate-AMPA/kainate receptor signalling from the alpha-cells has been proposed by Panzar and colleagues to play a critical role in the loss of counter-regulatory glucagon secretion from T1D islets in response to hypoglycemia." (PMID 38612880, 2024). "Detectable insulin concentrations concurrent with hypoketotic hypoglycemia as well as a robust glucose response (>30 mg/dL increase) to glucagon (1 mg) administration are diagnostic of hyperinsulinism." (PMID 38792494, 2024). "It is important to have glucagon available for patients at increased risk of level 2 or 3 hypoglycemia, and if the patient is unresponsive or unable to swallow, intravenous glucose or glucagon should be given by a trained person." (PMID 39851792, 2024). "This insufficient fasting glucagon levels partly supported the susceptibility to hypoglycemia in patients with T1D." (PMID 39149119, 2024). "Beta-blockers cause hypoglycemia probably through direct inhibition of hepatic production of glucose and release of glucagon." (PMID 39606700, 2024). "In Lean-NGT individuals, there is a time course increase in ICR, thus constraining plasma insulin concentrations, and possibly in response to the complete postprandial suppression in glucagon, thereby minimising the risk of hypoglycaemia." (PMID 39138690, 2024). "SF-1 regulation of glucagon release is evidently glucose-dependent as hypoglycemia causes loss of transcription factor control of this hormone profile." (PMID 39401164, 2024). "The second study used the BXD (C57BL/6J (B6) mice and DBA/2J (D2) mice) recombinant inbred GRP and identified the same locus on chromosome 8 associated with hypoglycemia-induced glucagon secretion." (PMID 39608054, 2024). "The deficiency of glucagon secretion from islet α-cells makes patients more susceptible to unpredictable episodes of hypoglycemia, even with carefully adjusted insulin doses." (PMID 39744270, 2024). "Although glucagon is used to increase blood glucose and prevent hypoglycemia, both animal and clinical studies have suggested that blocking glucagon signaling rarely causes hypoglycemia." (PMID 39217353, 2024). "In this phase, serum levels of insulin and glucagon and the body’s response to these hormones are unsatisfactory, making hormonal regulation inefficient, which can quickly cause hypoglycemia." (PMID 38756508, 2024). "This phenomenon suggests that α cells of FOXA1-deficient mice lose the ability to respond to hypoglycemia by increasing glucagon secretion." (PMID 36798663, 2023). "The secretion of glucagon by α-cells is primarily associated with occurrences of hypoglycemia, acting as a safeguard against low blood sugar levels." (PMID 37764697, 2023). "It regulates blood glucose via the incretin pathway, stimulating insulin and inhibiting glucagon secretion in a glucose-dependent manner, leading to lower blood glucose levels with low risk for hypoglycaemia." (PMID 37025414, 2023). "This suggests that an intake of protein is effective at reducing the post-exercise hypoglycemia risk, potentially via a glucagon-mediated stimulation of glucose production." (PMID 36771250, 2023). "Acute signs and symptoms are nausea, vomiting, abdominal pain, lethargy, convulsions, and/or progressive coma; impaired gluconeogenesis following fructose ingestion causes acute hypoglycemia refractory to glucagon." (PMID 37630734, 2023). "Further, two individuals reported that they have required an intramuscular glucagon injection due to severe hypoglycaemia associated with alcohol consumption (see illustrative case below)." (PMID 37864225, 2023).
Hypoglycemia (continued). "People with type 1 diabetes (T1D) are particularly susceptible to hypoglycemia due to the use of exogenous insulin and the loss of hypoglycemia-induced glucagon secretion." (PMID 37788058, 2023). "A potential means of reducing the risk of hypoglycemia using closed-loop systems is to add the glucose-elevating hormone glucagon." (PMID 36755913, 2023). "This is the first case documented of successful treatment with glucagon, anticonvulsants and intermittent mannitol for refractory hypoglycemia and seizure caused by fatal insulin overdose." (PMID 38026640, 2023). "To investigate effects of HNF1A loss on glucagon secretion during hypoglycemia, we performed i.p. insulin tolerance tests (IP-ITT)." (PMID 37943614, 2023). "GLP‐1 receptor agonists inhibit the release of glucagon, improve glucose control and also weight loss, and had a lower risk of hypoglycemia." (PMID 36544522, 2022). "Upregulation of CLIC1 was associated with glucagon, a hormone used to treat severe hypoglycemia, in the overall cohort (NCases = 129) (Overall-Spleen-CLIC1, p = 4.20 × 10−9) and in females (NCases = 78) (Females-Spleen-CLIC1, p = 1.4 × 10−8)." (PMID 35379376, 2022). "Decreased renal function, hypothyroidism, and disturbed glucose regulation mechanisms such as reduced glucagon and increased adrenalin release, inadequate glucose supply, and strict glycemic control management are risk factors for hypoglycemia." (PMID 36079032, 2022). "Previously developed models of glucose-dependent suppression of glucagon secretion have shown that, in hypoglycemia, the amplitude is sufficiently high to cause the opening of P/Q-type Ca2+ channels." (PMID 35448534, 2022). "Every patient taking insulin—even basal-only regimens—should be prescribed glucagon to treat severe hypoglycemia, and the patient’s family members and other close associates should be trained in how to administer it." (PMID 34922811, 2022). "In contrast, 2-O-M significantly enhances the secretion of glucagon and enhances liver gluconeogenesis to mitigate the risk of hypoglycemia." (PMID 35502441, 2022). "Further work should assess other barriers to guideline-concordant glucagon uptake among patients at risk of severe hypoglycemia." (PMID 36040744, 2022). "Aging can alter the glucose counter-regulation by dysregulating glucagon, growth hormone, and epinephrine responses to hypoglycemia and putting the elderly patient at risk of having hypoglycemia." (PMID 36371171, 2022). "Incretin hormones stimulate insulin secretion while inhibiting glucagon secretion in a glucose-dependent way, lowering blood glucose and reducing the risk of hypoglycemia and weight gain." (PMID 35512071, 2022). "Insulin and glucagon signaling are both dramatically dampened in Cavin1−/− mice, the Cavin1 deficiency leads to lethal neonatal hypoglycemia." (PMID 35723340, 2022). "Plasma glucagon quantification with an enzyme‐linked immunosorbent assay (ELISA) displayed a higher glucagon release in the hypoglycemia group starting at 3‐h post‐administration, consistent with the subsequent sustained normoglycemia levels." (PMID 35957510, 2022). "In individuals with T1D, the hormones that prevent hypoglycemia are typically impaired by the loss of glucagon release and a lesser release of epinephrine in response to declining levels of glucose in the blood." (PMID 36992764, 2022). "Another evolving avenue in research is the addition of glucagon to mitigate the risk of hypoglycemia and allow more aggressive insulin dosing." (PMID 35733769, 2022). "VGLUT2 deficient mice in SF1 neurons also had defective CRR to insulin-induced hypoglycemia and central 2-deoxyglucose, as this greater degree of hypoglycemia again linked to an impaired glucagon response." (PMID 34201257, 2021). "Understanding the SNS regulation of human α-cells has important implications for pathogenic mechanisms underlying dysregulation of glucagon secretion in patients with T1D related to hyperglycemia and hypoglycemia." (PMID 33753784, 2021).